YBX2 (Y-box binding protein 2)
Description:
Major constituent of messenger ribonucleoprotein particles (mRNPs). Involved in the regulation of the stability and/or translation of germ cell mRNAs. Binds to Y-box consensus promoter element. Binds to full-length mRNA with high affinity in a sequence-independent manner. Binds to short RNA sequences containing the consensus site 5'-UCCAUCA-3' with low affinity and limited sequence specificity. Its binding with maternal mRNAs is necessary for its cytoplasmic retention. May mark specific mRNAs (those transcribed from Y-box promoters) in the nucleus for cytoplasmic storage, thereby linking transcription and mRNA storage/translational delay (By similarity).
Synonyms: Dbpc; CSDA3; MSY2; Contrin
Tractability: PROTAC: ubiquitination databases record sites on it; its protein half-life has been measured.
Gene: Protein-coding gene on chromosome 17 (7,288,263 to 7,294,639, reverse strand). Ensembl gene ENSG00000006047.
Subcellular location: Cytoplasm; Nucleus
Gene Ontology:
Molecular function: nucleic acid binding
Biological process: positive regulation of cold-induced thermogenesis; regulation of gene expression; spermatogenesis; transcription by RNA polymerase II; translational attenuation; oocyte development
Cellular component: cytoplasm; nucleus
Genetic constraint (gnomAD): Loss-of-function variants: 5 observed, 39.54 expected, observed/expected ratio (o/e) 0.13, 90% interval 0.065 to 0.27. The upper end of that interval is the gene's LOEUF score, 0.27, which puts it in group 1 of 6, group 1 being the genes least tolerant of losing a copy. Missense variants: 417 observed, 477.65 expected, observed/expected ratio (o/e) 0.87, 90% interval 0.81 to 0.95. Synonymous variants: 187 observed, 189.61 expected, observed/expected ratio (o/e) 0.99, 90% interval 0.88 to 1.11.
Homologues: Orthologues: chimpanzee YBX2 (99% identical), macaque YBX2 (93% identical), dog YBX2 (90% identical), mouse Ybx2 (90% identical), pig YBX2 (90% identical), rat Ybx2 (90% identical), guinea pig YBX2 (90% identical), rabbit YBX2 (58% identical), tropical clawed frog ybx2 (52% identical), Drosophila melanogaster yps (35% identical), Caenorhabditis elegans cey-4 (21% identical), Caenorhabditis elegans cey-2 (19% identical), and 1 more. Paralogues in human: YBX1 (43% identical), YBX3 (40% identical), LIN28A (19% identical), LIN28B (19% identical).
Diseases named in the same sentence as YBX2 in open-access papers:
YBX2 is named in the same sentence as 38 diseases in open-access papers, as found by Europe PMC text mining. Sharing a sentence is not in itself a finding about the gene and the disease. The quoted sentences say what the papers report.
oral squamous cell carcinoma (10 papers, 2020 to 2022). "Moreover, YBX2 had been reported to be associated with the initiation and progression of oral squamous cell carcinoma." (PMID 33589575, 2021). "Meanwhile, it was found that LINC00958 promoted cell proliferation and migration in oral squamous cell carcinoma through the miR-627-5p/YBX2 axis." (PMID 35097114, 2022). "HOXA11-AS acts as a ceRNA that sponges miR-98-5p, thus regulating the expression of Y-box binding protein-2 in oral squamous cell carcinoma and, consequently, the progression of this disease." (PMID 36057597, 2022). "LINC00958 regulates the miR-627-5p/YBX2 axis to facilitate cell proliferation and migration in oral squamous cell carcinoma." (PMID 34660307, 2021). "A rescue study indicated that LINC00958 regulates the proliferation, motility, and EMT of oral squamous cell carcinoma cells through YBX2." (PMID 33557837, 2021). "YBX2 is remarkably up-regulated in oral squamous cell carcinoma and is a key target gene for the HOXA11-AS/miR-98-5p axis to regulate oral squamous cell carcinoma progression." (PMID 34819492, 2021). "A recent report showed that LINC00958 regulated the miR-627-5p/YBX2 axis and facilitated cell proliferation and migration in oral squamous cell carcinoma." (PMID 32095369, 2020). "For example, lncRNA HOXA11-AS upregulates YBX2 and accelerates the proliferation and metastasis of oral squamous cell carcinoma (OSCC) through competitively inhibiting miR-98-5p." (PMID 32984052, 2020). "YBX2 can act as an RNA binding protein (RBP) and it has been demonstrated to be up-regulated in a variety of tumors, including testicular seminoma, ovarian dysgerminomas, and oral squamous cell carcinoma." (PMID 34819492, 2021).
Azoospermia (6 papers, 2015 to 2023). Absence of any measurable level of sperm,whereby spermatozoa cannot be observed even after centrifugation of the semen pellet. "A recent study has shown that the mutation and polymorphism of YBX2, the human homologue of MSY2, are associated with azoospermia." (PMID 27483469, 2016). "Higher frequency of YBX2 polymorphism in azoospermia.Under expression of YBX2 gene." (PMID 36405559, 2022). "H1T2–chromatin IP/MS analysis also identified YbX2, another potential mRNA repressor involved in the regulation of translation whose knockout resulted in male infertility and azoospermia condition." (PMID 33407810, 2021). "Evidence regarding the participation of other RBPs in oocyte mRNA regulation, like Y-box binding protein 2 (YBX2) and deleted in azoospermia-like (DAZL), remain unclear." (PMID 37784186, 2023).
breast carcinoma (5 papers, 2017 to 2025). "YBX2 appears to contribute to molecular subtype-specific splicing in breast cancer." (PMID 34819492, 2021). "Comparison of the expression patterns of the m5C machinery across breast cancer subtypes revealed that the m5C methyltransferase NSUN5 and the readers ALYREF, YBX1, and YBX2 were overexpressed in the basal subtype relative to normal tissue." (PMID 40918643, 2025).
Infertility (4 papers, 2015 to 2018). "They showed a significant correlation between PRM2 mRNA deficiency and a lower YBX2 mRNA content in testicular spermatids of infertile men." (PMID 29766145, 2018). "Given this, we propose that the loss of translational repression in the compound Ybx2/3 heterozygote testes is the main driver for the observed infertility phenotype." (PMID 26646932, 2015). "This study showed t hat YBX2 gene has a potential role in male spermatogenesis, leading to male factor infertility." (PMID 25870841, 2015). "Ybx2-null mice are known to be infertile due to post-meiotic spermatid defects." (PMID 26646932, 2015). "Additionally, the “synthetic sterility” observed in compound Ybx2/3 heterozygotes suggests that for some of the roughly one in ten couples facing male-derived infertility, heterozygosity at two or more loci may be a driving factor." (PMID 26646932, 2015). "Double mutants could not be generated due to unexpected infertility in the compound Ybx2/3 heterozygotes." (PMID 26646932, 2015).
male infertility (4 papers, 2015 to 2026). The inability of the male to effect fertilization of an ovum after a specified period of unprotected intercourse. "Their results specified that YBX2 and JHDM2A genes may have an important role in male infertility and these two genes can be helpful biomarkers for diagnosis of male infertility." (PMID 27525322, 2016). "Generally, these data indicated that YBX2 and JHDM2A genes may playan important role in male infertility, and suggested that these molecules can act asuseful biomarkers for predicting male infertility." (PMID 25870841, 2015). "YBX2 and JHDM2A genes are germ-cell-specific molecules which are essential for the production of functional spermatozoa; therefore, their inactivation could lead to male infertility." (PMID 25870841, 2015).
endometrial cancer (2 papers, 2021 to 2024). Primary or metastatic malignant neoplasm involving the endometrium (mucous membrane that lines the endometrial cavity). "CT45 contributes to stemness associated with YBX2 and might be related to the progression of endometrial cancer." (PMID 33602962, 2021). "It has also been reported that YBX2 is correlated with the stemness, chemoresistance, malignancy and prognosis of endometrial cancer and lung cancer." (PMID 38698857, 2024). "In summary, our study demonstrated that the expression of YBX2 contributed to the stem cell-like phenotype in endometrial cancer stem cells." (PMID 33602962, 2021). "Moreover, there is significant proof indicating that YBX2 is involved in the maintenance of stem cells and the development of different types of tumors, such as oral and endometrial cancers." (PMID 38698857, 2024). "In this study, we clarified the function of YBX2 in endometrial cancer stem cells." (PMID 33602962, 2021). "First, we confirmed YBX2 protein expression in human endometrial cancer tissues." (PMID 33602962, 2021).
glioma (2 papers, 2021 to 2022). A benign or malignant brain and spinal cord tumor that arises from glial cells (astrocytes, oligodendrocytes, ependymal cells). "The combination of simultaneous knockdown of RPL32P3, YBX2, and HNF4G with DOX significantly induced U251 glioma cells apoptosis and produced the strongest effects." (PMID 34819492, 2021). "The simultaneous knockdown of RPL32P3, YBX2, and HNF4G combined with doxorubicin (DOX) increased the apoptosis of glioma cells." (PMID 34819492, 2021). "The results suggested that the combined application of knockdown of RPL32P3, YBX2, and HNF4G could promote the passage of DOX through BTB and enhance the inhibitory effect of DOX on glioma cells." (PMID 34819492, 2021). "In this study, by establishing the BTB model in vitro, we found that the simultaneous knockdown of RPL32P3, YBX2, and HNF4G combined with DOX could significantly increase the apoptosis rate of glioma cells." (PMID 34819492, 2021).
asthenospermia (1 paper, 2022). "Under expression of YBX2 gene in the blood and testis samples of azoospermic men compared to controls, oligospermia and asthenospermia." (PMID 36405559, 2022).
colon adenocarcinoma (1 paper, 2024). "Nevertheless, YBXs might have a safeguarding function in specific categories of malignancies, like YBX1 in colon adenocarcinoma (COAD) and thyroid carcinoma (THCA), and YBX2 in stomach adenocarcinoma (STAD)." (PMID 38698857, 2024).
colorectal adenocarcinoma (1 paper, 2024). The most common type of colorectal carcinoma. "On the other hand, YBXs have a defensive function in specific categories of cancers, like YBX1 in colorectal adenocarcinoma (COAD) and THCA, along with YBX2 in stomach adenocarcinoma (STAD)." (PMID 38698857, 2024).
endometrial adenocarcinoma (1 paper, 2024). "In contrast to the translational regulatory role of YTHDF3, Y-box binding protein 2 (YBX2) forms stable cytoplasmic condensates through recruiting YTHDF2 and promotes the degradation of m6A-modified HSPA6 mRNA in endometrial adenocarcinoma-derived Ishikawa cells." (PMID 39239525, 2024).
Flavivirus Infections (1 paper, 2023). Infections with viruses of the genus FLAVIVIRUS, family FLAVIVIRIDAE. "Male sensitivity to flavivirus infection may be due to YBX2 expression in testicular germ cells, as evidenced by the greater incidence of antibodies in males (32.3%) compared to females." (PMID 37446229, 2023).
glioblastoma (1 paper, 2021). The most malignant astrocytic tumor (WHO grade IV).
Globozoospermia (1 paper, 2015). Any structural anomaly of the acrosome resulting in a round sperm head. "Additionally, globozoospermia (round-headed sperm) was frequently observed in sperm from compound Ybx2/3 heterozygotes but not controls." (PMID 26646932, 2015).
liver cancer (1 paper, 2024). An epithelial or non-epithelial malignant neoplasm that arises from the liver. "Finally, experimental validations were conducted to explore that YBX2 might be a potential biomarker in liver cancer." (PMID 38698857, 2024).
uterine corpus endometrial carcinoma (1 paper, 2024). A endometrial carcinoma (disease) that involves the body of uterus. "YBX2 served as the determinant for ACC, specifically uterine corpus endometrial carcinoma (UCEC)." (PMID 38698857, 2024).
ZIKV infection (1 paper, 2023). "ZIKV infection is widely recognized as significantly reducing spermatogenesis after producing major physiological, immunological, and endocrine damage in the testes, most likely owing to YBX2 subtraction dysregulation." (PMID 37446229, 2023).
tumor (10 papers, 2006 to 2025). "We then established YBX2-knockdown cell lines, and evaluated cell survival, migration, invasion potential, as well as long-term growth and tumor formation effects using Transwell assays, MTT tests, and colony formation assays." (PMID 38698857, 2024). "REXO2, MSI1, and ESRP2 had high expression levels in tumors compared with normal tissues, while CTU1, MAEL, and YBX2 were undetermined in both tumor and normal tissues." (PMID 33193734, 2020). "In addition, YBX2 overexpression reversed the decrease in tumor cell viability and proliferation resulting from the overexpression of miR-18b-5p." (PMID 35156507, 2022). "In this study, YBX2 was highly expressed in OSCC cells, and overexpression inhibited OSCC cell apoptosis and enhanced tumor cell viability." (PMID 35156507, 2022). "Notable RBPs such as FUS (Fused in Sarcoma), YBX2 (Y-box Binding Protein 2), and AUF1 (AU-rich Element RNA-binding Protein 1) could regulate proliferation, migration, and invasion across various tumor cell types." (PMID 40538852, 2025). "Three potential binding proteins, including YBX1, YBX2 and PHB2, were selected for further validation considering their molecular weights, protein scores, subcellular localizations and potential involvement in tumour metastasis and progression." (PMID 37929660, 2024). "In addition, YBX2 expression notably increased in UM1 and HSC-2 cells, but decreased in miR-18b-5p overexpressed tumor cells." (PMID 35156507, 2022). "Also using our expression data, we identified several RNA processing factors that were differentially expressed between tumor subtypes and/or regulated by estrogen receptor, including YBX1, YBX2, MAGOH, MAGOHB, and PCBP2." (PMID 28263985, 2017). "Similarly, tumor cells may promote oncogenic expression through m5C, as suggested by the upregulation of its readers, YBX1, YBX2, and ALYREF, which enhance mRNA transport, stability, and translation." (PMID 40918643, 2025).
cancer (4 papers, 2006 to 2026). A tumor composed of atypical neoplastic, often pleomorphic cells that invade other tissues. "Y-box binding protein 2 (YBX2) has been associated with the properties of both germ cells and cancer cells." (PMID 33602962, 2021). "Because few studies have focused on the relationship between YBX2 and cancer stem cells, we examined how YBX2 contributed to the characteristics of CSCs." (PMID 33602962, 2021). "We hypothesized that YBX2 might contribute to the characteristics of cancer stem cells (CSCs)." (PMID 33602962, 2021). "This study examined the clinical features expression, prognostic value, mutations, along with methylation patterns of three genes from the YBX family (YBX1, YBX2, and YBX3) in 28 different types of cancer." (PMID 38698857, 2024). "Consistent with previous reports that cancer cells often exhibit defective ER stress signaling, we found that thapsigargin (TG) treatment enhanced IRE1α and PKAc phosphorylation and upregulated XBP1 target genes such as YBX2 and TGFβ2." (PMID 41516347, 2026). "Finally, we validated the increased expression of YBX2 in some HCC cell lines and its correlation with enhanced HCC proliferation, migration, and invasion, thereby addressing our previous pan-cancer analysis findings." (PMID 38698857, 2024).
YBX2 also shares sentences with these, for which no sentence is quoted: bladder cancer (1 paper); cervical cancer (1); digestive system carcinoma (1); dysgerminoma (1); embryonal carcinoma (1); female infertility (1); germ cell tumours (1); head and neck squamous cell carcinoma (1); hepatocellular carcinoma (1); metabolic disease (1); oligospermia (1); ovarian dysgerminomas (1); seminoma (1); teratoma (1); testicular mixed germ cell tumours (1); testicular seminoma (1); testicular tumor (1); thyroid carcinoma (1); yolk sac tumours (1).